HELLS (helicase, lymphoid specific)
Diseases named in the same sentence as HELLS in open-access papers (continued):
Sharing a sentence is not in itself a finding about the gene and the disease.
tumor (continued). "Besides, we selected 5 key genes (SRSF2, HELLS, PNN, TK1, and CKS2) in hallmark_E2F_targets in Pathcards database and validated that they are associated with overall survival, metastasis, and tumor stage of patients with PCa through multiple online database validation." (PMID 35392496, 2022). "Previous studies have shown that HELLS is regulated through the RB/E2F pathway and that loss of RB1 results in upregulation and overexpression of HELLS, a process that may contribute to epigenetic changes that drive tumor progression." (PMID 32071286, 2020). "One hypothesis is that HELLS overexpression leads to increased de novo DNA methylation of tumor suppressor genes, thereby decreasing the transcriptional level of tumor suppressor genes and increasing the incidence of tumor." (PMID 32071286, 2020). "Our previous study showed that miR-150-3p (the passenger strand) was significantly suppressed in LUSQ tissues, and performed a tumor-suppressive role in LUSQ cells via controlled several cell cycle-related genes, including HELLS." (PMID 37508549, 2023). "The results revealed that the mean methylation levels of G6PD, HELLS, RRM2, and STMN1 were significantly lower in HCC tissues than in peri-tumor tissues." (PMID 36304446, 2022). "Of the same family, the enzyme helicase lymphoid-specific (HELLS) was also found to be overexpressed in HCC patients and significantly correlated with poor prognosis due to augmented tumor aggressiveness." (PMID 34680398, 2021). "Other groups and we have identified HELLS as a transcriptional downstream target gene of E2F1 that is overexpressed in cancer and contributes to tumor progression." (PMID 32071286, 2020). "As we had determined EZH2 protein expression on the similar cohort, we analysed the expression of HELLS and EZH2 in similar tumor areas." (PMID 27191985, 2016). "Using orthotopic human xenografts, we validated that upregulation of HELLS and UHRF1 is essential for the tumor phenotype." (PMID 25338120, 2014). "We speculate that highly proliferating tumor cells might specifically rely on HELLS for proficient SSB repair, while HELLS might be dispensable for SSB repair in slowly proliferating, non-tumor cells." (PMID 41297801, 2025). "When specificially examining the tumor samples alone, we found that the cycling HepT population expressed high levels of EZH2, SUZ12, and EED, along with cell cycle regulators MKI67, AURKB, ASPM, TOP2A, and HELLS." (PMID 40766612, 2025). "Expression of HELLS in non-tumor cerebellar cells is low or non-existent, making HELLS an attractive, tumor-specific target for research." (PMID 31541170, 2019). "MP-HX downregulated the expression of genes that could promote anti-apoptotic effect, cell cycle progression, tumor development and progression, which include BIRC5, CCNA2, CCNB1, CCNB2, CCNE2, CDK1/2/6, GINS2, HELLS, MCM2/10 PLK1, RRM2 and SKP2." (PMID 30042885, 2018). "However, HELLS upregulation may not always be synonymous to a critical role in tumorigenesis or tumor progression, or a warranted target for therapeutics in all malignancies where HELLS overexpression is observed." (PMID 30220967, 2018). "Finally, by comparing tumor (T) and non-tumorous tissue (NT) tissue in the TCGA HCC (LIHC) cohort we only found overexpression of HELLS, but not other members of the SNF2 family in HCC based on log2 fold change cut off of ≥/≤ ±1.0 and p-value cut off of ≤0.05." (PMID 35053620, 2022).
cancer (42 papers, 2009 to 2026). A tumor composed of atypical neoplastic, often pleomorphic cells that invade other tissues. "Our studies demonstrate that loss of HELLS in cancer cells phenocopies several key characteristics associated with SSB deficiency." (PMID 41297801, 2025). "ICC (Immunocytochemistry) and ELISA (Enzyme-Linked Immunosorbent Assay) revealed that HELLS knockdown decreased 5-hydroxymethylcytosine (5hmC) and increased 5-methylcytosine (5mC) levels in four cancer cell lines." (PMID 40175344, 2025). "The HELLS SNF2 family remodeler has been implicated in the regulation of key cancer-driving pathways, including proliferative signaling, oncogenic transcriptional programs, and DDR." (PMID 41297801, 2025). "HELLS has been implicated in several cancer pathways, including proliferative signaling, genome instability, deregulated cell energetics, and invasion, all of which influence many aspects of cancer initiation, progression, and responses to therapy." (PMID 41297801, 2025). "The chromatin remodeler HELLS (helicase, lymphoid specific) has emerged as an important epigenetic regulator of DNA repair, genome stability, and multiple cancer-associated pathways." (PMID 36012581, 2022). "HELLS has been linked with several signaling pathways important for cancer development and progression, beyond the RB/E2F pathway." (PMID 36012581, 2022). "HELLS has been implicated in several cancer pathways, associated with proliferative signaling, genome instability, deregulated cell energetics, and invasion." (PMID 36012581, 2022). "HELLS has a broad and diverse regulatory role in cancer and is closely linked to well-known molecules or pathways regulating cancer which have important implications for cancer therapy." (PMID 35774795, 2022). "Cox regression analysis of the 33 cancers showed that HELLS expression in 12 cancers was significantly associated with OS." (PMID 35774795, 2022). "HELLS is mutated or misregulated in tumour samples from several cancer types and is also mutated in some cases of immunodeficiency-centromeric instability-facial anomalies syndrome (ICF), characterized by instability within pericentromeric repeats." (PMID 31802118, 2020). "In some of these cancers, mutations are present, resulting in increased HELLS levels or activity, however, in other cases HELLS levels are decreased or its function is abrogated." (PMID 31541170, 2019). "Emerging reports have linked HELLS overexpression in cancers with its ability to promote proliferation." (PMID 30220967, 2018). "Furthermore, we found that HELLS is co-expressed with PARP1 in cancer cells, and its loss is synthetic lethal with homologous recombination deficiency (HRD)." (PMID 41297801, 2025). "HELLS is frequently mutated or overexpressed in many types of cancer." (PMID 36012581, 2022). "HELLS is highly expressed in many cancers and is a potential diagnostic and prognostic marker." (PMID 35774795, 2022). "The SNF2 family chromatin remodeler HELLS has emerged as an important regulator of cell proliferation, genome stability, and several cancer pathways." (PMID 41297801, 2025). "This work unveils new functions of HELLS in modulating SSB repair and responses to clinically relevant DNA alkylation damage, thus offering new insights into the potential therapeutic value of targeting HELLS in cancer." (PMID 41297801, 2025). "Decreased proliferative capacity in HELLS KO cells is consistent with other studies and highlights an important function of HELLS in cancer cell growth and proliferation." (PMID 41297801, 2025). "HELLS is expressed in highly proliferating cells of the lymphoid tissue, germ cells, and stem cells, and it is substantially elevated in cancer cells." (PMID 41297801, 2025). "HELLS was found to be highly expressed in a variety of cancer cells and serves as a poor prognostic biomarker." (PMID 39944833, 2025).
cancer (continued). "Here, we determined the expression levels of HELLS mRNA and protein in human organs, tissues, and cell lines and compared them with those found in various cancers." (PMID 35774795, 2022). "Our results also showed that HELLS activates the EMT pathway in cancers and that HELLS expression positively correlates with EMT in AML." (PMID 35774795, 2022). "We explored the role of HELLS in cancers using The Cancer Genome Atlas (TCGA) and Genotype-Tissue Expression (GTEx) database." (PMID 35774795, 2022). "We observed that HELLS was mutated infrequently in 32 cancers and 6% of the UCEC population had HELLS mutations, which was the highest of all cancer types." (PMID 35774795, 2022). "Our study aims to provide a more systematic and comprehensive understanding of the role of HELLS in the development and progression of multiple malignancies through analysis of HELLS in cancers." (PMID 35774795, 2022). "The role of HELLS in cancer has received a lot of attention from researchers in the past years, and aberrant HELLS expression is reportedly involved in the development of a variety of malignancies and is linked to poor prognosis in these tumors." (PMID 35774795, 2022). "Among the 32 cancers, shallow deletion was common in the expression of HELLS mRNA in all cancers except AML, ACC, DLBC, PCPG, THYM, THCA, and UVM." (PMID 35774795, 2022). "In conclusion, our study elucidated the role of HELLS in pan-cancer from various angles, including its relevant signaling pathways, mutation sites, and relation to immune cell infiltration." (PMID 35774795, 2022). "Here, we review and summarize accumulating evidence highlighting important roles for HELLS in DNA repair, genome maintenance, and key pathways relevant to cancer development, progression, and treatment." (PMID 36012581, 2022). "The AUC of the ROC exceeded 0.7 in 27 cancers and 0.9 in 14 cancers, suggesting that increased HELLS expression contributes to the development of many cancers and can be a new diagnostic marker in clinical practice." (PMID 35774795, 2022). "For molecular subtypes, HELLS expresses significantly differently in five cancer types, including ACC, KIRP, LIHC, LUSC and PRAD." (PMID 35774795, 2022). "HELLS activates or inhibits several famous pathways in cancers, suggesting that HELLS regulates tumors through various mechanisms." (PMID 35774795, 2022). "We therefore analyzed HELLS expression in the immune and molecular subtypes of these cancers and 21 other cancers." (PMID 35774795, 2022). "Our present study of LUSQ cells confirmed that depletion of HELLS attenuates cancer cell aggressive phenotypes." (PMID 34944699, 2021). "None of the signature genes except TERT was cataloged by the expert-curated Cancer Gene Census44 (as of July 2020), although LIN9 and HELLS were recently implicated in cancer." (PMID 33420056, 2021). "Given that HELLS is frequently overexpressed in human cancers, these results have prompted several investigations for its role in cancer epigenome regulation." (PMID 32840881, 2021). "This function of HELLS in maintenance of genome stability is likely to contribute to its role in cancer biology and demonstrates that different chromatin remodelling activities are required for efficient repair in specific genomic contexts." (PMID 31802118, 2020). "According to recent research, HELLS also plays an important regulatory role in cell proliferation and, possibly, in the development of cancer." (PMID 32195055, 2020). "Significant upregulation of HELLS has been reported in 33 human cancer types." (PMID 41297801, 2025). "Furthermore, HELLS-deficient cells display synthetic lethality with inhibition of RAD51, highlighting the potential therapeutic value of targeting HELLS in cancer." (PMID 41297801, 2025). "HELLS is a chromatin remodeling ATPase that provides chromatin-accessible regions for methyltransferase enzymes and affects the expression of various genes in cancer cells." (PMID 37945594, 2023).
cancer (continued). "This suggests that HELLS mRNA can be a serum biomarker for metastasis in some cancers." (PMID 35774795, 2022). "The discrepancies in levels of SCE might be attributed to different cell types, mouse lymphocytes vs human cancer cells, and involvement of HELLS in different aspects of DNA repair and genome maintenance." (PMID 36012581, 2022). "HELLS expression correlates positively with Tcm cells in many cancers." (PMID 35774795, 2022). "It was found that HELLS was overexpressed in cancer lesions of LUSQ tissue." (PMID 34944699, 2021). "Furthermore, knockdown of HELLS was found to decrease the expression of numerous metabolic genes and inhibit ferroptosis, a newly recognized programed cell death in cancer." (PMID 33280236, 2021). "Consequently, aberrant HELLS expression is closely linked to the malignant progression of several cancers, suggesting that HELLS is a candidate therapeutic target for these cancers." (PMID 34944699, 2021). "Therefore, HELLS appears to play a role in transcriptional regulation in cancer cells through at least two different mechanisms, functioning as a chromatin remodeler and/or a scaffold protein for recruiting other chromatin modifiers." (PMID 32840881, 2021). "It will be of interest to determine whether HELLS upregulation also affects genome stability or if its impact on cancer progression is due to another mechanism such as transcriptional misregulation of genes that drive proliferation." (PMID 31802118, 2020). "Therefore, targeting HELLS in cancer could potentially lead to a synergistic response of halting rapid cell proliferation and hyper-sensitizing cancer cells to chemotherapy, and/or PARP inhibitors." (PMID 41297801, 2025). "Here, several growth-associated genes were up-regulated, including RNA helicase (HELLS), PRR11, CDCA8, and DNA topoisomerase 2 (TOP2A), HMGB2, EIF2B4, and CDKN3, which are thought to serve important functions during growth stimulation, many of which are known to be up-regulated in various cancers." (PMID 37907238, 2024). "HELLS may also regulate cancer by mediating DNA repair and cell cycle." (PMID 35774795, 2022). "Since HELLS and PARP1 are known to be frequently overexpressed in many cancer types, we sought to determine if HELLS and PARP1 are co-expressed at the RNA and protein level by analyzing the TCGA and CPTAC web portals." (PMID 41297801, 2025). "Importantly, our data imply cell type specificity of HELLS function, suggesting that highly proliferating cancer cells with elevated HELLS expression might rely on HELLS for SSB repair, whereas HELLS might be dispensable in slowly proliferating, non-transformed cells with low HELLS expression." (PMID 41297801, 2025). "Up-regulation of HELLS in CRC promotes the proliferation and migration of cancer cells, and HELLS knockdown induces G2/M arrest in CRC49." (PMID 37945594, 2023). "Intriguingly, top five upregulated genes are all linked to regulation of oncogenesis and metastasis and pan cancer analysis of TCGA dataset revealed that these genes have co-occurrence of expression in cancers including CRYAB with BSG and HELLS." (PMID 36624493, 2023). "HELLS indirectly repairs DNA damage by positively regulating C-NHEJ and HR, affecting genomic homeostasis and cancer regulation." (PMID 35774795, 2022). "Here, HELLS negatively correlated with apoptosis in LUAD at the single-cell level, suggesting that HELL-mediated apoptosis regulation mechanisms differ across cancers." (PMID 35774795, 2022). "Especially, 7 of ATPCRs showed a significant overexpression in multiple cancer types, including TTF2 (n = 6), RAD54L (n = 4), ACTL6A (n = 4), CHD7 (n = 3), HELLS (n = 3), HLTF (n = 3), and ACTR5 (n = 3)." (PMID 35789070, 2022).
cancer (continued). "We also studied the role of helicase, lymphoid specific (HELLS), a chromatin remodeling protein identified as a critical downstream effector of the RB-E2F signaling pathway in various cancers." (PMID 30220967, 2018). "We also examined the role of HELLS, a chromatin remodeling protein transcriptionally regulated by E2F1 that promotes tumorigenesis in several cancers." (PMID 30220967, 2018). "The co-expression of HELLS and PARP1 in cancer might imply potential functional interactions between HELLS and PARP1." (PMID 41297801, 2025). "Our studies identify HELLS as an important regulator of the BER/SSBR pathway, which could serve as a potential therapeutic target in the sensitization of cancer cells to alkylation chemotherapy and PARPi, especially in the context of HR deficiency." (PMID 41297801, 2025). "Although HELLS is not widely expressed in all normal tissues, our results from TCGA and GTEx show that its expression was significantly higher in most cancers than in normal tissues." (PMID 35774795, 2022). "Almost all the FRGs in signaling pathways of pan-cancer, STMN1, RRM2, HELLS, FANCD2, and AURKA could significantly activate the cell cycle, but inhibit EMT, DNA damage response, hormones ER, RAS/MAPK, and RTK." (PMID 36349201, 2022). "The role of HELLS in some of these cancers has not been reported and there are also previously unexplored mechanisms or pathways that regulate progression in the cancers where HELLS has been reported." (PMID 35774795, 2022). "Lymphoid-specific helicase (LSH/HELLS), a chromatin-remodeling ATPase complex, belongs to the sucrose non-fermentable 2 (SNF2) family and plays a vital role in the normal life processes of animals, plants, and cancer progression." (PMID 33002417, 2021). "Interestingly, our current proteomics data now place MYSM1 in a functional network with PCNA, RFC, HELLS, and MCMBP with potential relevance in hematopoiesis and in cancer progression." (PMID 32466590, 2020). "The co-expression of HELLS and PARP1 in multiple cancer types is significant and implies that HELLS might cooperate with PARP1 in regulating various aspects of DDR and/or DNA damage tolerance, promoting cancer cell proliferation and survival despite the elevated DNA damage." (PMID 41297801, 2025). "This could explain why differential HELLS expression does not affect survival in certain cancers, whereas its varied expression in different molecular or immune subtypes plays a different role in the prognosis of various cancers." (PMID 35774795, 2022). "This may be due to the fact that although the overall frequency of HELLS mutations in cancer is not high, we can see that the majority of HELLS mutations in PRAD are Deep deletion, and the number of samples with Deep deletion in HELLS mRNA expression is highest in PRAD compared to other cancers." (PMID 35774795, 2022). "Additionally, exposure to mifepristone downregulated the expression of several apoptotic genes, including BIRC5 and HELLS, while increased the expression of SLC7A11, a transporter involved in ferroptosis, an iron-dependent cell death that has been shown to be regulated in PDAC and other cancers." (PMID 36359879, 2022).